BECN1 (beclin 1)
Diseases named in the same sentence as BECN1 in open-access papers (continued):
Sharing a sentence is not in itself a finding about the gene and the disease.
cancer (continued). "These components can also be used to target cancer-progressing autophagy regulators like Beclin-1, mTOR, NFkB, Erk, Akt, and ROS." (PMID 37893079, 2023). "Consistent with previous studies, the attenuated-Beclin-1 levels in SH-SY5Y cells were correlated with the induction of apoptosis through interaction with Bcl-2 antiapoptotic members in cancer cells." (PMID 37529115, 2023). "The expression of the four essential autophagy proteins and their association with cancer aggressiveness has been studied (the microtubule-associated protein 1 light chain 3A–LC3A, LC3B, Beclin 1, p62, lactate dehydrogenase 5–LDH5)." (PMID 36769263, 2023). "Phycocyanin induces autosis in addition to apoptosis in cancer cells (pancreatic), and phycocyanin treatment leads to increased Beclin 1 expression and NF-κB nuclear translocation." (PMID 37091978, 2023). "Naringenin, also tentatively identified in this sub-fraction, has shown an inhibitory effect on human AGS cancer cells by activating autophagic proteins Beclin 1 and LC3B, with significant phosphorylation of mitogen-activated protein kinases (MAPKs)." (PMID 36615543, 2023). "P62/SQSTM1, LC3 and Beclin‐1 are critical proteins involved in the overall process of autophagy and function in cancer development." (PMID 37665055, 2023). "There are conflicting reports regarding the relationship between BECN1 expression and prognosis in human cancers." (PMID 36830954, 2023). "For example, cullin 3 (CUL3)-mediated beclin 1 (BECN1) degradation inhibits autophagy and promotes cancer progression." (PMID 37394582, 2023). "BECN1 can promote ferroptosis through the regulation of activity of the cysteine and glutamate antiporter system xc– in cancer cells." (PMID 36702843, 2023). "These seminal findings underscore the critical role swof Beclin 1‐mediated autowphagy in cancer development and highlight the significance of understanding this molecular pathway for potential therapeutic interventions." (PMID 37837401, 2023). "We showed that SNX29 expression was associated with most genes in most cancers, such as ATG2B, EPG, AMBRA1, and BECN1, in most cancers." (PMID 36829159, 2023). "Beclin-1 not only acts as a key autophagic regulator and its specific interactor but also represents a potential therapeutic target for cancer." (PMID 37269429, 2023). "BECN1 plays a central role in autophagy, which is essential for self-renewal of CSCs and the maintenance of cancer stemness." (PMID 35488273, 2022). "Other miRNAs, such as miR-216a, miR-17-5p, miR-26a or miR-30a, that specifically target Beclin-1, support the idea that induction of autophagy after cancer therapy triggers resistance." (PMID 35309939, 2022). "Beclin-1 expression was lower in cancer cells, heterozygous disruption of BECN1 promotes tumorigenesis, and its overexpression inhibits tumorigenesis." (PMID 35309939, 2022). "Oppositely, the IHC result showed that the BECN1 protein expression was significantly lower in HCC tissues than in adjacent non-cancer liver tissues." (PMID 36295086, 2022). "Some other BH3 mimetics are shown to disrupt the interaction between Beclin 1:Bcl-2 and induce autophagy of various cancer cells, namely gossypol, obatoclax, and ABT-737." (PMID 36309485, 2022). "Cancer cells halt in G2, die by autophagy detected through an increase in Beclin-1, and a decrease in the LC3-I/LC3-II ratio and the p62 marker." (PMID 35280788, 2022). "Beclin-1 was known for its ability to affect the sensitivity of cancer to targeted therapy such as gefitinib, osimertinib and sorafenib, but was not involved in autophagy-dependent resistance to erlotinib in tongue squamous carcinoma." (PMID 35690866, 2022). "It is possible that cancer cells utilize the alternative splicing of BECN1 for modulating autophagy and mitophagy in response to environmental stresses." (PMID 36008963, 2022).
cancer (continued). "It has been shown that HCQ, as an autophagy inhibitor, can suppress the activity of BNIP3 and Beclin-1 in mesenchymal cancer cells, leading to significantly reduced spheroid formation." (PMID 35821262, 2022). "The BECN1-induced ferroptosis requires AMP-activated protein kinase (AMPK)-mediated phosphorylation of BECN1 at Ser90/93/96 when cancer cells are exposed to system xc− inhibitors, e.g., erastin, sulfasalazine, and sorafenib." (PMID 36552652, 2022). "Tat-BECN1 is widely tested as an autophagy activator for basic and translational research, and shows great therapeutic potential in cancers, neurodegenerative diseases, infectious diseases, injury recoveries, aging and so on." (PMID 36172279, 2022). "The activation of autogenesis, such as beclin-1 passes through autophagy to promote cancer cell survival." (PMID 36147496, 2022). "Mechanistically, Beclin-1 facilitates PP2A mediated degradation of c-Myc, leading to decreased cell division and cancer cell proliferation, indicating that Beclin-1 acts as a haploinsufficiency tumor suppressor gene (TSG) in cancer." (PMID 35252196, 2022). "have observed that p62 and Beclin-1 were increased after treating Se NPs in cancer cells for 12 h, suggesting that the late phase of autophagy was inhibited by Se NPs." (PMID 35958612, 2022). "Our results show that different BECN1 isoforms can have diverse effects on autophagy, underlining the importance to investigate the presence of alternative splicing isoforms of BECN1 in cancer and their role in autophagy." (PMID 36008963, 2022). "For example, an autophagy defect resulting from knocking down BECN1 (beclin 1) promotes the formation of cancer in mice." (PMID 36497321, 2022). "Increased HNRNPA1 expression is found in multiple cancer types, and positively correlates with BECN1 expression, and is proposed to mediate cancer development." (PMID 35585060, 2022). "Studies have shown the downregulation of Beclin 1 and upregulation of Bcl-2 in many types of cancers, both were closely related to poor prognosis." (PMID 36676047, 2022). "Unsurprisingly, cancer cachexia patients show elevated levels of beclin-1 as well as increased levels of the autophagy marker protein, LC3B-II." (PMID 36531941, 2022). "The results of Western blotting suggested that the expression of autophagy-related proteins LC-3, ULK1, and Beclin-1 was decreased in cancer tissues, while CDM treatment led to a dose-dependent increase in their expression." (PMID 35126526, 2022). "The initial connection between autophagy and cancer was established when studies demonstrated that Beclin-1 is mono-allelically deleted in approximately 50% of breast, ovarian, and prostate cancers." (PMID 35359388, 2022). "Beclin‐1 and Bcl‐2 family pathways have been reported to involve in the regulation of autophagy in cancer cells." (PMID 35106915, 2022). "Regarding the TRAF6-BECN1 signaling axis for cancer progression in response to TLR4 stimulation (depicted in the left), TRAF6 can interact with BECN1 and induce ubiquitination of BECN1, leading to the induction of autophagy (indicated as a black arrow)." (PMID 35422093, 2022). "Cancer cells die by autophagy with Beclin-1 accumulation, LC3-II formation, p62 degradation, and RAPTOR phosphorylation in the mTOR complex." (PMID 35280788, 2022). "In conclusion, our study adds evidence to the existence of different BECN1 isoforms in cancer and shows that their presence can alter autophagy in distinctive ways." (PMID 36008963, 2022). "What confer the sensitivity of HIV-infected cells, cancer cells and ischemic neurons to Tat-BECN1-induced cytotoxicity?" (PMID 36172279, 2022). "In the current study, expression of the autophagy markers LC3B and beclin-1 increased in both the respiratory and limb muscles of the cancer-cachectic mice, and treatment with rucaparib elicited a significant decline in the same muscles." (PMID 35740560, 2022).
cancer (continued). "One of the masters ncRNAs regulators of Beclin-1 is miR-30a, whose role has been described in several types of cancer and its overexpression has been regarded to have a positive impact on cancer progression." (PMID 35309939, 2022). "ATG5/12 and Beclin 1 overexpression in cancer cells promoted LC3-II expression and inhibited p62 accumulation, indicating upregulation of autophagic flux." (PMID 35449123, 2022). "In fact, it has been investigated the relation between cancer aggressiveness and the expression of the four major autophagy proteins (the microtubule-associated protein 1 light chain 3A–LC3A, LC3B, Beclin 1, p62, lactate dehydrogenase 5–LDH5)." (PMID 35409187, 2022). "In SK-ES-1 cells (anaplastic osteosarcoma or ES cell line), Beclin-1 knockdown strongly decreased the basic cancer properties of the cell line, such as proliferation, migration, and invasion." (PMID 33652741, 2021). "Autophagy was previously thought to play a protective role against cancer development, as evidenced by the monoallelic deletion of Beclin-1 and autophagy inactivation in breast, ovarian and prostate cancer." (PMID 33743781, 2021). "This is supported by the fact that monoallelic Becn1 loss led to deregulation of the mammary cell hierarchy due to immature MEC expansion and resulted in more aggressive basal and TNBC-like cancers in WNT1-driven mammary tumorigenesis." (PMID 34207792, 2021). "To evaluate the role of IL-6-induced BECN1 Y333 phosphorylation in cancer therapy, we first used a CRC model and assessed the potential role of IL-6 in CRC chemotherapy resistance." (PMID 34131122, 2021). "Deregulation of c-Myc correlated with increased tumorigenesis in Beclin-1 defective systems, suggesting that Beclin-1 acts as a haploinsufficiency tumor suppressor gene in cancer." (PMID 33976943, 2021). "On the other side, TF SMAD3 was identified to involve in cancer progression by regulating its target genes BECN1, GLI2, and E4BP4." (PMID 33802957, 2021). "Beclin-1 is a crucial regulator for autophagy initiation and its dysfunction has been identified in several cancer types." (PMID 33652741, 2021). "Recent studies have described ROS can regulate autophagy through the regulation of autophagy gene expression such as Beclin‐1 or P62 in cancer cells." (PMID 33960631, 2021). "In contrast, TLR4 enhances autophagy induction through beclin 1 (BECN1) ubiquitination by TNF receptor-associated factor 6 (TRAF6) promoting cell migration and invasion in various cancer cell lines." (PMID 34575052, 2021). "Knockdown of Beclin-1 by RNA interference (RNAi) blocks ferroptosis, whereas knocking of Beclin-1 by gene transfection promotes ferroptosis in cancer cells in response to system xc− inhibitors (e.g., erastin, sulfasalazine, and sorafenib)." (PMID 34007410, 2021). "Several subsequent studies have connected BECN1 with different types of cancer, such as hepatocellular carcinoma, gastric cancer and lymphoma." (PMID 34829881, 2021). "Cisplatin was previously shown to generate autophagy in cancers through activation of Beclin-1 and Atg5, followed by the conversion of LC3-I to LC3-II." (PMID 34321115, 2021). "In the present study, we showed that BECN1 Y333 phosphorylation enhances BECN1 activation and promotes cancer chemotherapy resistance." (PMID 34131122, 2021). "Autophagy inhibition in MCF7 cancer cells, through silencing of BECN1, restored the CTL lysis capability in the same model." (PMID 34944772, 2021). "Autophagic mediators, including ATGs, PI3K, mTOR, and Beclin-1, can integrate into cancer cell signaling networks and ultimately determine cell survival or death." (PMID 34093198, 2021). "Hypoxia in cancer cells increases RAGEs expression and in cancer the involvement of the AGE-RAGE axis promotes the autophagic activity via the activation of autophagic proteins such as Beclin-1 with inhibition of apoptotic signaling." (PMID 34194625, 2021).
cancer (continued). "Aside from BECN1, few haploinsufficient models of autophagy have been studied in the context of cancer." (PMID 31923184, 2020). "Beclin 1 overexpression suppressed the proliferation of both cancer cells, evidenced by CCK-8 (P<0.05)." (PMID 33425768, 2020). "The pro-autophagy gene beclin-1 is commonly deleted in several types of cancer, such like breast, ovarian, and prostate cancer, suggesting a tumor suppressor function in the autophagy pathway." (PMID 32235610, 2020). "Inhibition of Beclin-1 provokes an increased tumorigenesis, while an increased expression of Beclin-1 reduces the development of cancers in animal experimentations." (PMID 33704184, 2020). "Here we investigate the metabolic impact of anti-cancer treatment, starvation and Tat-Beclin 1 induced autophagy in cancer cells." (PMID 31517566, 2020). "According to Kaplan-Meier plotter, Becn1 expression was found to positively correlate with overall and progression-free survival rates of all cancer patients (P<0.05), even stratified by Lauren’s classification, TNM staging and treatment (P<0.05)." (PMID 33425768, 2020). "Changes in the transcriptional activity of the BECN1 indicated a decreased expression of this gene in all cancer clinical stages (CSI–CSIV)." (PMID 33322704, 2020). "On the other hand, SNAIL and TWIST are degradated by the autophagy-lysosome degradation machinery in cancer cells upon PI3K or Beclin-1 overexpression, and vice versa." (PMID 32707662, 2020). "Meanwhile, the expression of autophagy related gene BECN1 mRNA expression was assayed and found that the BECN1 mRNA expression in cancer tissues was remarkably lower than that in normal tissues (P < 0.01)." (PMID 32626525, 2020). "BECN1 is also an essential gene required for embryonic survival and development, but also for the development of cancer and several neurodegenerative diseases." (PMID 32674313, 2020). "Beclin‐1 serves not only as a key autophagic regulator with its specific interactors, but also as a potential therapeutic target in cancer." (PMID 31955515, 2020). "As a key factor in autophagy, BECN1 should act as an oncogene in cancer, but the roles of BECN1 in cancers are still unclear." (PMID 32358527, 2020). "Several studies indicate that receptor and non-receptor tyrosine kinases regulate autophagy activity in cancer, and some suggest the importance of Beclin 1 tyrosine phosphorylation in this process." (PMID 33287140, 2020). "Autophagy inhibition inhibits cancer initiation at an early stage, as indicated by downregulation of Beclin 1 and upregulation of p62 expression." (PMID 33335896, 2020). "We additionally knocked down 14‐3‐3ζ in hypoxic cancer cells and found that, under hypoxia, 14‐3‐3ζ barely affected BECN1 gene expression at translational level." (PMID 31709727, 2020). "As BthTX-I increased Beclin-1 expression,we concluded that this toxin induced autophagy conjointly with apoptosis in thebreast cancer cell lines herein investigated." (PMID 31384244, 2019). "All these results together with our present data indicate that BECN1 functions as an oncogene at least in some kind of cancer cells or under certain circumstance." (PMID 31272261, 2019). "We further discovered that BECN1 interacted with Vimentin, which was implicated in epithelial–mesenchymal transition (EMT) and cancer cell migration." (PMID 31272261, 2019). "In detail, LC3A/B and Beclin 1 were expressed both in the cytoplasm and in the nucleus of the cancer cells, while AMBRA-1 was preferentially localized in the nucleus, mainly in high grade cases." (PMID 30893939, 2019). "An exception to this general scheme is represented by the tumor suppressor BECN1 (ATG6), which lost with high frequency one allele in various cancer types." (PMID 31027346, 2019).
cancer (continued). "Clinic studies have confirmed that the cancer incidence increased after Beclin-1 was suppressed, such as ovarian, breast, and prostate cancers." (PMID 31126310, 2019). "The mechanism by which autophagy is induced has been widely reported, and inhibition of the AKT/mTOR, ROS/AMPK, and Bcl-2/Beclin-1 signaling pathways are known to induce autophagy in cancer cells." (PMID 30627053, 2019). "Tanshinone IIA, one of the main compounds of S. miltiorrhiza Bunge, has been shown to inhibit the growth of cancer cells via autophagy and apoptosis, which is related to the Beclin-1/Atg7/Atg12-Atg5 and PI3K/Akt/mTOR pathways." (PMID 31406500, 2019). "Until now, the role of BECN1 in cancer cell migration is still contradictory and the molecular mechanism is not clear." (PMID 31272261, 2019). "Beclin-1 (BECN1) is an autophagy regulator and potential tumor suppressor in multiple cancers, including NSCLC35." (PMID 31101821, 2019). "MiR-34a-5p downregulation observed in many tumors would positively affect BECN1 expression, leading to enhanced autophagy, but the effect of this improved autophagic flux is likely to be dependent on cancer type, cancer stage, and cell type." (PMID 31608105, 2019). "A growing body of research has shown that Beclin-1 knockout mice are more prone to spontaneous cancers." (PMID 31126310, 2019). "The results showed that PCDH17 and BECN1 were highly expressed in the cytoplasm of cancer cells, and their expression was significantly correlated (p < 0.05)." (PMID 31815010, 2019). "AKT, PI3K, mTOR, p62, LC3, and Beclin 1 showed consistent downregulation of gene expressions in Lanatoside C treated cancer cells compared to untreated cells." (PMID 31783627, 2019). "LC3A/B and Beclin 1 were expressed both in the cytoplasm and in the nucleus of neoplastic elements, mainly in high grade cancers; AMBRA-1 was preferentially localized in the nucleus." (PMID 30893939, 2019). "Taken together, these data suggest that a decreased Beclin 1 expression occurs frequently in tumors when compared to normal samples, and it also suggest that lower Beclin 1 levels usually correlate with a worse prognosis in multiple cancer types." (PMID 31877888, 2019). "Dissociation of Bcl-xL and Beclin-1 induces autophagy in cancer cells, and mutation of the BH3 domain in Beclin-1 alters Bcl-xL-mediated autophagy indicating regulatory roles of Bcl-xL in cell degradation." (PMID 30463183, 2018). "Protein expression patterns also differed between the non-cancer and the cancer cell lines for pS6RP and beclin-1." (PMID 30372478, 2018). "Meanwhile, the release of Beclin 1 initiates excessive autophagy, which induces type II programmed death in cancer cells." (PMID 30304783, 2018). "When there are defects in autophagy induction (for instance, due to the monoallelic deletion of Beclin-1), cells are more easily transformed into cancer cells." (PMID 30344951, 2018). "For example, haploinsufficiency of BECN1 is frequently observed in several forms of human cancer including breast." (PMID 29262563, 2017). "By uncovering the sequence of regulations which finally lead to the elimination of cancer cells we were able to identify BECN1, NOXA and Survivin as initial key players in MG-2477-induced cell death." (PMID 28415610, 2017). "To verify our discovery regarding role of Beclin 1 in ER-positive breast cancer cells, we investigated relationship between Beclin 1 and patients’ survival using IHC staining of Beclin 1 of patients’ cancer tissue." (PMID 28881721, 2017). "In fact, an autophagy-independent role for Beclin 1 loss was reported to contribute to the enhanced cancer stem cell maintenance and tumorigenesis that was observed in WNT1/BECN1+/−mice." (PMID 28881721, 2017). "Especially, Beclin 1 is a key role in human pathogenesis especially in cancer, however, expression and function of Beclin 1 in different cancers, even in different stages of the same cancer, was not consistent." (PMID 28881721, 2017).